RN7SL121P (RNA, 7SL, cytoplasmic 121, pseudogene)
Gene: Miscellaneous RNA gene on chromosome 19 (2,595,019 to 2,595,291, reverse strand). Ensembl gene ENSG00000263974.
Homologues: Paralogues in human: RN7SL718P (86% identical), Metazoa_SRP (85% identical), RN7SL602P (84% identical), Metazoa_SRP (84% identical), Metazoa_SRP (83% identical), RN7SL525P (82% identical), Metazoa_SRP (82% identical), Metazoa_SRP (81% identical), RN7SL387P (79% identical), Metazoa_SRP (79% identical), Metazoa_SRP (78% identical), RN7SL524P (78% identical), and 712 more.